OXT (oxytocin/neurophysin I prepropeptide)
Diseases named in the same sentence as OXT in open-access papers (continued):
Sharing a sentence is not in itself a finding about the gene and the disease.
psychiatric disorder (continued). "As was implied, being able to assess the relation between central OXT from peripheral measurements (e.g. blood, saliva) is crucial to understand the effect of this hormone in social behavior or to postulate its usefulness as a clinical marker in different psychological or psychiatric disorders." (PMID 34805562, 2021). "Additionally, it was found that OXT had modulatory effects on social behaviors, including attachment, maternal behavior, mating, sexual behavior, and aggression, and showed significant improvements toward social deficits involved in psychiatric disorders, especially in ASD." (PMID 37153633, 2023). "Oxytocin (OXT) and arginine vasopressin (AVP) have become promising targets for psychiatric disease treatment." (PMID 36430254, 2022). "The review summarizes the aberrant OXT/OXTR signaling in behavioral deficits and psychiatric disorders, contributing to the understanding of the neurobiology of psychiatric disorders and providing insights into the progress of OXTR-related neurodevelopmental disorders." (PMID 37153633, 2023). "In addition, we highlight the importance of polygenic approaches for the fruitful understanding of the OXT and AVP signaling mechanisms and the studies on the effect of intranasal OXT and AVP infusions on psychiatric disorders." (PMID 26858594, 2015).
tumor (18 papers, 2015 to 2025). "To extend and validate the effects of l-fucose and OXT, we treated mice with l-fucose in combination with OXT and found that the addition of OXT to l-fucose therapy resulted in significantly increased tumor shrinkage." (PMID 38979515, 2024). "Mechanical injury, tumor compression, and surgical damage to the hypothalamus and related structures can cause impairment of other functions, including memory, social behavior, and emotion, which may be related to a deficiency in OXT caused by damage to the hypothalamic-pituitary system." (PMID 38796566, 2024). "Remarkably, combination treatment with OXT and l-fucose ameliorates tumor burden in CAC development." (PMID 38979515, 2024). "Histologically, OXTRfl/fl mice treated with OXT showed reduced tumor areas, less colon injury, and immune cell infiltration." (PMID 38979515, 2024). "The combined analysis revealed sex, race, TMB, neoplasm histologic grade, Child–Pugh grade, MMRN1, OXT and COX6A2 transcription as independent risk factors." (PMID 36153509, 2022). "Indeed, we found higher serum OXT level in the OSCC cohorts, which may due to tumor stress, a condition associated with all OSCC patients." (PMID 36045118, 2022). "Sex, race, TMB, neoplasm histologic grade, Child–Pugh grade, MMRN1, OXT and COX6A2 transcription have been identified as independent risk factors." (PMID 36153509, 2022). "On the other hand, serum OXT levels were significantly elevated in OSCC patients when compared with either healthy people or patients with leucoplakia and increased significantly as the tumor progressed (median: 81.21 pg/ml in OSCC patient vs 16.5 pg/ml in healthy people)." (PMID 36045118, 2022).
cancer (13 papers, 2016 to 2023). A tumor composed of atypical neoplastic, often pleomorphic cells that invade other tissues. "In summary, this study employed a novel approach to investigate the molecular mechanism underlying the diverse effects of OXT on cell-cell contacts, proliferation, and migration in a 3D spheroid environment, which provides the basis for a better understanding of degenerative diseases and cancer." (PMID 36263085, 2022). "Those neuron-specific OXT effects are translatable to other cell types, especially cancer cells, where OXT affects proliferation and cellular migration in a cell-type-specific way." (PMID 36263085, 2022). "While most of the early studies on OXT and cancer have been conducted in classical two-dimensional cultures, we know nowadays that a 3D environment and cell-matrix interactions alter basic cellular characteristics and can affect the cellular response to certain stimuli." (PMID 36263085, 2022). "Previous studies have also identified a novel link between OXT and cancer." (PMID 36172369, 2022). "However, the role of OXT/OXTR signaling in different cancers seems to be inconsistent." (PMID 36045118, 2022).
neurodevelopmental disorder (12 papers, 2013 to 2026). A behavioral and cognitive disorder with onset during the developmental period that involves impaired or aberrant development of intellectual, motor, or social functions. "Although the function of glutamate‐OXT circuits in the context of social behaviors remains unknown, both glutamate and OXT have been separately implicated in neurodevelopmental disorders characterized by deficits in social behavior." (PMID 34786775, 2021). "Finally, we explore the potential convergence between the OXT system and genes associated with neurodevelopmental disorders, focusing on the SHANK3 gene." (PMID 29970997, 2018). "However, the mechanisms underlying the dysregulation of OXT/OXTR signaling in neurodevelopmental disorders remain unclear." (PMID 37153633, 2023). "Increasing evidence warranted that aberrant OXT/OXTR signaling is an essential factor in the neuropathology of some neurodevelopmental disorders." (PMID 37153633, 2023). "We also reviewed findings from genetic rodent models of neurodevelopmental disorders that demonstrate alterations in the OXT system." (PMID 29970997, 2018). "The objective of this review is to provide a framework for the role OXT plays in modulating synaptic plasticity and its implication in neurodevelopmental disorders." (PMID 29970997, 2018). "Despite the major interest in the therapeutic potential of OXT to treat social behavior deficits, there is still a considerable gap in the knowledge about the plausible implication of the OXT system in the pathogenesis of neurodevelopmental disorders." (PMID 29970997, 2018). "We then highlight studies that report specific alterations in the OXT system in rodent models of neurodevelopmental disorders." (PMID 29970997, 2018). "The mechanisms underlying the dysregulation of OXT/OXTR signaling in neurodevelopmental disorders are not fully understood." (PMID 37153633, 2023). "Indeed, OXT regulates the “GABA switch”, which is linked to the onset of neurodevelopmental disorders." (PMID 32438751, 2020). "Hence, due to the inconsistency between humans and animals findings, further adequate studies are necessary to elucidate whether OXT has therapeutic potential for social deficits or others involved in neurodevelopmental disorders." (PMID 37153633, 2023). "Therefore, we conclude that OXT could constitute a potential therapeutic strategy for the treatment of neurodegenerative and neurodevelopmental disorders through its anti-inflammatory and neuroprotective properties." (PMID 32438751, 2020). "However, little attention has been paid to the possible implication of the OXT system in neurodevelopmental disorders and to whether perturbation in OXT may contribute to the social behavior phenotype." (PMID 29970997, 2018). "Understanding the specific sites within the brain where OXT exerts its rescue action is a fundamental step to strengthening the rationale for its use in PWS/SYS and further neurodevelopmental disorders." (PMID 36998737, 2023). "In humans, OXT was found to improve social deficits, such as face recognition and social responsiveness, in ASD or other neurodevelopmental disorders." (PMID 37153633, 2023). "Several mouse models of neurodevelopmental disorders present abnormalities in OXT release and/or OXTR distribution, providing a strong rationale for the use of OXT as a possible therapeutic agent." (PMID 36998737, 2023). "Importantly, given the etiological and phenotypic heterogeneity in ASD and neurodevelopmental disorders, we do not expect impairment in the OXT system to explain the behavioral phenotypes of all individuals with the disorder." (PMID 29970997, 2018).
neurological disorders (6 papers, 2020 to 2026). "In addition to being linked to metabolic disorders, OXT signaling is associated with neurological disorders and behavioral and psychiatric functions." (PMID 31912136, 2020). "The findings of our study may help clarify the relationships among OXT, neurological disorders, and AD, as well as the protective mechanism of OXT and the clinical benefits of its mediation in AD." (PMID 40143166, 2025). "Our findings may have translational value since altered OXT and AVP mechanisms in humans have been implicated in ASD and other psychiatric and neurological disorders;;;." (PMID 34687351, 2022). "To obtain further information about the proportion of NLGN4-expressing cells among AVP/OXT-producing neurons, we additionally examined PVNs and SONs in cases that had been excluded from the study owing to the presence of neurodevelopmental or neurological disorders." (PMID 36747195, 2023). "In addition to OXT, several other genes associated with neurological diseases were also dysregulated in both the SO diets but not the CO diet." (PMID 31912136, 2020).
cardiovascular diseases (4 papers, 2021 to 2025). "Based on PICRUSt2 statistical analysis, OXT intervention significantly reduced the abundance of microbial taxa associated with cardiovascular diseases in the OXT+APP/PS1‐SI group compared to the NaCl+APP/PS1‐SI group (p < 0.05)." (PMID 40635450, 2025). "Therefore, it was concluded that the pathogenesis of cardiovascular diseases can be significantly influenced by the dysregulation of OXT production and OXTR expression, especially in such disorders as ischemia, hypoxia, inflammatory disturbances, pain, and stress conditions." (PMID 36835321, 2023).
metabolic disease (4 papers, 2013 to 2020). A congenital disorder (due to inherited enzyme abnormality) or acquired (due to failure of a metabolically important organ) disorder resulting from an abnormal metabolic process. "Altogether, these results indicated that OXT peptide engineering can help optimize the therapeutic effects for metabolic diseases." (PMID 23700406, 2013). "Thus, with the structural modifications, [Ser4, Ile8]-OXT can potentially outperform OXT in treating metabolic diseases." (PMID 23700406, 2013). "Of importance, our studies showed that peripheral administration of OXT can stimulate the central release of OXT to induce metabolic effects, provoking us to test if the method of peripheral OXT delivery could be developed to treat metabolic diseases in human patients." (PMID 23700406, 2013).
neurodegenerative disease (4 papers, 2019 to 2025). A disorder of the central nervous system characterized by gradual and progressive loss of neural tissue and neurologic function. "OXT plays a critical role in the pathogenesis of AD, particularly in regulating social interaction and emotional balance in neurodegenerative diseases." (PMID 40635450, 2025). "In this context, oxytocin (OXT), which is a neuropeptide, has antioxidant effects that may benefit a range of neurodevelopmental and neurodegenerative diseases." (PMID 40143166, 2025). "OXT significantly increased peroxisomal function and antioxidant system defense capability, therefore illustrates that OXT might be an alternate treatment approach for the neurodegenerative diseases like HD." (PMID 31089364, 2019).
infection (3 papers, 2017 to 2026). The state of being infected such as from the introduction of a foreign agent such as serum, vaccine, antigenic substance or organism. "The results showed that high infection rates in AVP-positive neurons (56.68%) and CRH-positive neurons (25.93%), whereas infection of OXT-positive neurons was minimal (9.09%)." (PMID 41543628, 2026).
brain disorder (2 papers, 2013 to 2025). A disease affecting the brain or part of the brain. "Indeed, we have confirmed the antioxidant effects of OXT, which is aligned with many studies that have been reported on brain disorders." (PMID 40143166, 2025).
immune disorders (1 paper, 2019). "Although the OXT system is abnormal in FES patients, the immuno-inflammatory indicators are normal in this study, suggesting that immune disorders might not be the main contributor of SZ." (PMID 31024366, 2019).
proliferative retinopathies (1 paper, 2023). "Of them, the topical application of CL-717 as eye drops is clinically the most appealing as it raises the possibility of treating proliferative retinopathies, including DR, without intraocular injections of OXT-328 or Q-922 injected either intraocularly or intraperitoneally." (PMID 37172294, 2023).
OXT also shares sentences with these, for which no sentence is quoted: migraine (6 papers); myocardial infarction (5); alcohol use disorder (4); Anorexia (3); breast carcinoma (3); Osteopenia (3); asthma (2); atherosclerosis (2); cardiac hypertrophy (2); Headache (2); morbid obesity (2); polycystic ovary (2); prostate diseases (2); sarcopenia (2); separation anxiety disorder (2); sleep-disordered (2); Adult onset (1); alcohol addiction (1); alexithymia (1); amenorrhea (1); aneurysm (1); Anosmia (1); Arrhythmia (1); autoimmune disease (1); AVP deficiency (1); benign prostatic hyperplasia (1); cerebral artery (1); cleft lip/palate (1); cocaine abuse (1); colorectal adenocarcinoma (1).
A further 49 diseases each share a sentence with OXT in 1 paper.